RHOU (ras homolog family member U)
Description:
Binds to and activates protein kinase PAK1. Plays a role in the regulation of cell morphology, cytoskeletal organization and focal adhesion assembly during cell migration. Also stimulates quiescent cells to reenter the cell cycle. Has no detectable GTPase activity but its high intrinsic guanine nucleotide exchange activity suggests it is constitutively GTP-bound.
Synonyms: WRCH-1; ARHU; CDC42L1; G28K; WRCH1; DJ646B12.2; FLJ10616; hG28K; fJ646B12.2
Tractability: Small molecule: a structure with a bound ligand is known. Antibody: UniProt places it where antibodies can reach, with high confidence; its Gene Ontology location is reachable by antibodies, with high confidence. PROTAC: UniProt records ubiquitination sites on it; ubiquitination databases record sites on it.
Gene: Protein-coding gene on chromosome 1 (228,735,479 to 228,746,664, forward strand). Ensembl gene ENSG00000116574.
Subcellular location: Cell membrane; Golgi apparatus membrane; Cell junction, focal adhesion; Cell projection, podosome
Subcellular location (Human Protein Atlas): Microtubules; Primary cilium
Pathways (Reactome):
Immune System: Interleukin-4 and Interleukin-13 signaling
Signal Transduction: RHOU GTPase cycle
Gene Ontology:
Molecular function: protein binding; protein-macromolecule adaptor activity; guanyl-nucleotide exchange factor activity; protein kinase binding; G protein activity; GTP binding; GTPase activity
Biological process: positive regulation of establishment of protein localization to mitochondrion; positive regulation of focal adhesion disassembly; actin filament organization; endocytosis; establishment of cell polarity; regulation of small GTPase mediated signal transduction; small GTPase-mediated signal transduction
Cellular component: focal adhesion; Golgi membrane; plasma membrane; cytosol; endosome membrane; podosome
Genetic constraint (gnomAD): Loss-of-function variants: 9 observed, 20.85 expected, observed/expected ratio (o/e) 0.43, 90% interval 0.26 to 0.75. The upper end of that interval is the gene's LOEUF score, 0.75, which puts it in group 3 of 6, group 1 being the genes least tolerant of losing a copy. Missense variants: 258 observed, 306.6 expected, observed/expected ratio (o/e) 0.84, 90% interval 0.76 to 0.93. Synonymous variants: 161 observed, 134.15 expected, observed/expected ratio (o/e) 1.2, 90% interval 1.05 to 1.37.
Homologues: Orthologues: chimpanzee RHOU (100% identical), macaque RHOU (99% identical), pig RHOU (95% identical), rat Rhou (92% identical), mouse Rhou (92% identical), rabbit RHOU (79% identical), zebrafish rhoua (72% identical), guinea pig RHOU (59% identical). Paralogues in human: RHOV (53% identical), CDC42 (43% identical), RAC1 (42% identical), RAC3 (42% identical), RHOQ (41% identical), RAC2 (41% identical), RHOJ (40% identical), RHOG (37% identical), RHOA (34% identical), RHOC (33% identical), RHOB (33% identical), RHOBTB2 (32% identical), and 10 more.
Diseases named in the same sentence as RHOU in open-access papers:
RHOU is named in the same sentence as 29 diseases in open-access papers, as found by Europe PMC text mining. Sharing a sentence is not in itself a finding about the gene and the disease. The quoted sentences say what the papers report.
prostate carcinoma (10 papers, 2012 to 2025). A carcinoma that arises from epithelial cells of the prostate gland. "Immunohistochemical staining revealed that the increased expression of FASN, RhoU and Cdc42 was associated with prostate cancer aggressiveness." (PMID 32139877, 2020). "Our results suggest that levels of RhoU and Cdc42 expression in prostate cancer cells are associated and could be correlated with disease progression." (PMID 32139877, 2020). "Here, we show that RhoU overexpression in prostate cancer cells increases cell migration and invasion." (PMID 38180080, 2024). "We find that RhoU homodimerizes in prostate cancer cells and that this is mediated by its C-terminal extension." (PMID 38180080, 2024). "RhoU mRNA expression is upregulated in prostate cancer and is considered a marker for disease progression." (PMID 38180080, 2024). "RhoU expression is upregulated in prostate cancer and has been suggested to be a prognostic indicator for prostate cancer progression, along with other genes." (PMID 38180080, 2024). "Upregulated RhoU in prostate cancer correlated with disease progression, and silencing of RhoU was shown to reduce the migratory ability of MDA-MB-231 and PC3 breast cancer cells." (PMID 36221055, 2022). "Further, in vitro Fasn inactivation by shRNA affects the adhesion, migration, and invasion of prostate cancer cell lines via actin cytoskeletal remodeling, achieved by decreasing the palmitoylation of the GTPase RhoU and consequent inactivation of Cdc42." (PMID 33166087, 2021). "FASN depletion leads to decreased RhoU palmitoylation and impaired RhoU activity, and thus the down-regulation of paxillin serine phosphorylation and reduced migration phenotype in prostate cancer." (PMID 34803494, 2021). "Taken together this analysis strongly suggests the involvement of RhoU and Cdc42 in prostate cancer progression." (PMID 32139877, 2020). "We discovered that depletion of FASN in prostate cancer leads to a decrease in the palmitoylation of the atypical Rho GTPase RhoU." (PMID 32139877, 2020). "To test the clinical significance of our findings we analysed FASN, RhoU and Cdc42 in prostate cancer and adjacent benign tissue in a cohort of 85 men who underwent a radical prostatectomy." (PMID 32139877, 2020). "Silencing of three genes (DLX1, PLA2G7 and RHOU) in the prostate cancer cell lines PC3 and VCaP by siRNA resulted in marked growth arrest and cytotoxicity, particularly in 3D organotypic cell culture conditions." (PMID 27196083, 2016). "Knockdown of RhoU expression by RNAi in prostate cancer cell lines reduces migration and invasion." (PMID 38180080, 2024). "To confirm this hypothesis, we demonstrated that depletion of RhoU leads to the same changes in adhesion dynamics in prostate cancer cells." (PMID 32139877, 2020). "The other selected genes are HIST1H1E, LRAT, LCN2, KCNN4, RHOU, and EPHA5 in the order of them entering the model, among which LRAT, LCN2, RHOU, and EPHA5 are known to link to prostate cancer, and HIST1H1E and KCNN4 are connected to myeloma and pancreatic cancer, respectively." (PMID 29100492, 2017).
breast carcinoma (7 papers, 2019 to 2024). "Several studies have shown that RHOU is up-regulated in various cancers, such as T-cell acute lymphoblastic leukemia, prostate cancer, multiple myeloma, and breast cancer." (PMID 35454871, 2022). "Our previous work, in breast cancer, reported that depletion of RhoU expression led to increased peripheral adhesions and reduced paxillin S272 phosphorylation; the same phenotype observed here in FASN knockdown cells." (PMID 32139877, 2020). "To assess the functional role of RHOU in this context we analyzed the highly aggressive basal-like breast cancer cell line MDA-MB-231, whose motility and invasivity have been shown to require the expression of the non-canonical WNT5a and WNT5b ligands." (PMID 30654518, 2019). "Additionally, in breast cancer cells, depletion of RHOU expression resulted in impaired cell migration and invasion." (PMID 35454871, 2022). "RhoU down-regulation by silencing or treatment with JNK, SP1 or STAT3 inhibitors leads to impaired migration and invasion in basal-like MDA-MB-231 and BT-549 cells, suggesting that STAT3 and SP1 can cooperate to induce high RhoU expression and enhance breast cancer cells migration." (PMID 30654518, 2019). "Other molecules regulate STAT3-modulated breast cancer metastasis, such as proto-oncogene serine/threonine-protein kinase (PIM1), miRNA, Mucin-1-C (MUC1-C), natriuretic peptide receptor A (NPRA), and RhoU." (PMID 34488773, 2021). "STAT3 also stimulates the expression of high Ras Homolog Family Member U (RhoU) by collaborating with Specificity Protein 1 (SP1), leading to breast cancer cell migration." (PMID 34488773, 2021). "The silencing of RhoU has been shown to reduce the migratory capacity of PC3 and MDA-MB-231 breast cancer cells." (PMID 32139877, 2020).
myeloma (3 papers, 2017 to 2022). "Here we demonstrate that RHOU is heterogeneously expressed in primary multiple myeloma cells and significantly modulated with disease progression." (PMID 29440639, 2018). "In multiple myeloma cells, decreased RHOU expression using siRNA reduced their cell migration." (PMID 35454871, 2022). "Since RhoU can alter cell adhesion, actin dynamics, and cell motility, we aimed at testing if this protein could mediate these cellular features in myeloma cells and if changes in its expression, and thus activity, might lead to BM niches remodeling." (PMID 29440639, 2018).
basal cell carcinoma (2 papers, 2011 to 2021). A carcinoma involving the basal cells. "We detected another integration in the RHOU gene, which has been associated with basal cell carcinoma." (PMID 33557409, 2021).
dental caries (2 papers, 2012 to 2013). The decay of a tooth, in which it becomes softened, discolored, and/or porous. "For example, two genes PTK2B and RHOU were suggested to be candidate loci previously, and they are involved in pathways that have been implicated to dental caries." (PMID 24146904, 2013). "Though biologically plausible, it is currently unknown whether RHOU is involved in genetic susceptibility to dental caries." (PMID 23259602, 2012). "In general, we identified several suggestive loci (P-value ≤ 10E-05) within or near genes with plausible biological roles for dental caries, including RPS6KA2 and PTK2B, involved in p38-depenedent MAPK signaling, and RHOU and FZD1, involved in the Wnt signaling cascade." (PMID 23259602, 2012).
melanoma (2 papers, 2015 to 2023). A malignant, usually aggressive tumor composed of atypical, neoplastic melanocytes. "Another particular event we found was the overexpression of RHOU in metastatic cell lines compared to primary tumor cells, and this is of interest because it encodes for a Rho GTPase involved in cell motility through lamellipodia formation, highlighting its potential role in melanoma invasion." (PMID 37047539, 2023). "While nothing is known about the role of RHOQ and RHOU in melanomagenesis, RHOJ participates to chemoresistance through DNA repair control and modulates metastasis potential in melanoma." (PMID 26098773, 2015).
biliary atresia (1 paper, 2020). A rare, biliary tract disease characterized by progressive obliterative cholangiopathy of the intra- and extrahepatic bile ducts, occurring in the embryonic/ perinatal period, leading to severe and persistent neonatal jaundice and acholic stool. "Biopsies of patients with biliary atresia demonstrated increased RhoU/Wrch1 and Hey2 expression in cholangiocytes." (PMID 32371929, 2020).
breast tumors (1 paper, 2019). "Here, we identify the SP1 transcription factor as an essential mediator of RhoU transcriptional activation downstream of the WNT/PCP pathway, and we unveil a functional cooperation between WNT/PCP/JNK1, RHOU, SP1 and STAT3 to promote cell motility in basal-like human breast tumor cells." (PMID 30654518, 2019).
colorectal cancer (1 paper, 2021). A primary or metastatic malignant neoplasm that affects the colon or rectum. "Increased RHOU expression was detected in the EGFR PC9-CR cells, while the well-known oncogene in lung and colorectal cancer TLE4 was also induced by cisplatin in the PC9-CR cells." (PMID 34065402, 2021).
hepatocellular carcinoma (1 paper, 2024). A malignant tumor that arises from hepatocytes. "Firstly, we detected the expression level of RHOU, AnxA6 and SENP1 protein in mouse orthotopic hepatoma tissues." (PMID 38566133, 2024).
Insulin resistance (1 paper, 2019). Increased resistance towards insulin, that is, diminished effectiveness of insulin in reducing blood glucose levels. "MYO5B, DLG2, RHOU, and SNCA are novel biomarkers for the development of insulin resistance." (PMID 30678306, 2019).
leukaemia (1 paper, 2016). "RHOU is also functionally linked to Notch1 signaling in leukaemia, where T-ALL cell migration is stimulated by RHOU upregulation, leading to enhanced motility and dissemination of leukaemia cells." (PMID 27196083, 2016).
liver cancer (1 paper, 2024). An epithelial or non-epithelial malignant neoplasm that arises from the liver. "Compared with mouse normal liver tissues, the IHC staining revealed that the levels of SENP1 and RHOU were a relatively high expression in mouse liver cancer tissues, but AnxA6 was decreased." (PMID 38566133, 2024).
mastitis (1 paper, 2022). Inflammation of breast tissue during lactation or postpartum due to an obstructed duct or infection. "Other noteworthy genes (RHPN2, ACSS2, RHOU, and KRT7) showing lower expression in cows with mastitis have critical roles in biological pathways, cellular process, fatty acid synthesis, and metabolism." (PMID 35723402, 2022).
neuroblastoma (1 paper, 2012). Neuroblastoma (NB) is the most common solid, extracranial childhood tumor. "For example RhoU, RhoBTB1 and especially Rnd2 are expressed in neuroblastoma, while Rnd3 is expressed in HeLa and neuroblastoma." (PMID 22916134, 2012).
ovarian carcinoma (1 paper, 2022). A malignant neoplasm originating from the surface ovarian epithelium. "ISG15, SNCA, RIPK2, PLCG2, RHOU, TRIB2 and ELP2 influenced the OS and PFI of ovarian cancer patients in the TCGA-OV dataset, while RIPK2 also affected the OS and PFI of ovarian cancer patients treated with Taxol in the GSE30161, GSE32062 and GSE63885 datasets." (PMID 35477477, 2022).
T-cell acute lymphoblastic leukaemia (1 paper, 2015). "It has been reported that T-cell acute lymphoblastic leukaemia, a strongly Notch- dependent cancer, up-regulates Wrch-1/RhoU in a Notch activity-dependent manner to promote cell migration and chemotaxis." (PMID 26208319, 2015).
triple-negative breast carcinoma (1 paper, 2019). An invasive breast carcinoma which is negative for expression of estrogen receptor (ER), progesterone receptor (PR), and human epidermal growth factor receptor 2 (HER2). "Importantly, our data also show the cooperative regulation of RhoU, and of RhoU-mediated triple negative breast cancer cells migration and invasion, by WNT/JNK1/SP1 and STAT3." (PMID 30654518, 2019).
cancer (10 papers, 2015 to 2024). A tumor composed of atypical neoplastic, often pleomorphic cells that invade other tissues. "GALNTL5 interacts with RHOU, a Rho‐related GTP‐binding protein implicated in cancer cell migration (reviewed in Ref." (PMID 33426787, 2021). "Thus, SP1 activity is required to enhance cell migration downstream of the aberrant activation of the WNT/PCP/JNK pathway in basal-like cancer cells, at least partly via the induction of RHOU expression." (PMID 30654518, 2019). "No point mutations related to cancer have been reported for RHOU or RHOV to date." (PMID 35454871, 2022). "Compared with the corresponding adjacent non-cancer tissues, the level of SENP1 and RHOU was upregulation in HCC tissues, but AnxA6 level was downregulation." (PMID 38566133, 2024). "Here, we performed further analyses and characterization of HBV integrations identified by our recently reported VIcaller platform in recurrent or known HCC genes (such as TERT, MLL4, and CCNE1) as well as non-recurrent cancer-related genes (such as CSMD2, NKD2, and RHOU)." (PMID 33557409, 2021).
tumor (10 papers, 2016 to 2025). "Atypical Rho proteins have so far been implicated in multiple activities including tumour suppression (e.g. RhoBTB2), cell transformation and -morphogenesis as well as development (e.g. RhoU and Rnd)." (PMID 34793580, 2021). "As a result, cyclin dependent kinase 6 (CDK6) and ras homolog family member U (RHOU) have been identified as potent biomarkers for predicting the tumor invasiveness in patients with NF-PitNET." (PMID 32498309, 2020). "Our data establish a clear functional correlation between constitutive activation of the PCP pathway, JNK activity, SP1-mediated RhoU transcription and tumor cell motility." (PMID 30654518, 2019). "In contrast, several factors assigned to the suppression of tumor cell migration and/or invasion as well as angiogenesis, such as DLC1, RHOU, DACH1, and RECK, were significantly downregulated in the brain-seeking cell line in comparison with the native one." (PMID 35163822, 2022). "Mechanistically, the authors could demonstrate that abolition of RHOU expression within the intestinal epithelium caused a hyperplastic phenotype affecting all IEC subtypes associated with reduced apoptosis and increased proliferation, which also occur in RHOU-deficient tumor cell lines." (PMID 33406731, 2021). "The small GTPase RhoU was identified as a WNT1 target gene, mediating tumor transformation and promoting cell migration/invasion by inhibiting the formation of focal adhesions." (PMID 30654518, 2019). "They used the extraction of exosomal mRNA and detection of mRNA expression of candidate genes related to tumor progression or invasion, such as cyclin-dependent kinase 6 (CDK6), ras homolog family member U (RHOU), and spire type actin nucleation factor 2 (SPIRE2)." (PMID 40362297, 2025). "We recently identified RhoU as a STAT3 target gene downstream of gp130 cytokines, and reported a positive correlation between STAT3 activation and RHOU expression levels in a panel of human tumor cell lines, including MDA-MB-231 cells." (PMID 30654518, 2019). "In addition, silencing of PLA2G7, RHOU, ACSM1, LAMB1 and CACNA1D also resulted in reduced tumor cell invasion in PC3 organoid cultures." (PMID 27196083, 2016). "Interestingly, overexpression of RHOU, a Rho GTPase involved in cell motility through lamellipodia formation, was observed in metastatic cells (p < 0.0001, eight times higher in VMM1 and two times higher in MNT-1) when compared to primary tumor cells." (PMID 37047539, 2023). "Investigated molecules without connection to common key tumor proteins are GNAS, USP8, USP48, HHIPL1, NNAT, RHOU, C5orf66 and RASSF3, which seem to be more specific biomarkers and therefore should be validated for concordant differences in liquid biopsies." (PMID 32498309, 2020).
RHOU also shares sentences with these, for which no sentence is quoted: multiple myeloma (2 papers); astrocytomas (1); Ductal carcinomas (1); lung adenocarcinoma (1); metastatic melanoma (1); pancreatic cancer (1); prostate tumor (1); serous ovarian cancer (1); T-cell lymphomas (1).